CCL2 (C-C motif chemokine ligand 2)
Diseases named in the same sentence as CCL2 in open-access papers (continued):
Sharing a sentence is not in itself a finding about the gene and the disease.
bladder cancer (continued). "Furthermore, statistical analysis revealed that LNMAT1 levels were positively correlated with CCL2 expression levels in bladder cancer specimens (r = 0.647, p < 0.001)." (PMID 30237493, 2018). "These facts indicate that CCL2 blockade may be effective in both chemotherapy-based first-line therapy and immune checkpoint inhibitor-based second-line therapy in the treatment of bladder cancer." (PMID 34445235, 2021). "Therefore, we examined whether VEGF-C is involved in LNMAT1-induced lymphangiogenesis and whether LNMAT1-induced CCL2 excretion by bladder cancer cells could induce VEGF-C expression in TAMs." (PMID 30237493, 2018). "Moreover, high CCL2 expression was associated with poor OS and DFS in 266 bladder cancer patients." (PMID 30237493, 2018). "Finally, we examined whether the LNMAT1/CCL2/lymphangiogenesis axis identified in vivo was clinically relevant to bladder cancer." (PMID 30237493, 2018). "Therefore, our results show that LNMAT1-induced CCL2 might play dual roles in the lymphatic metastasis of bladder cancer cells." (PMID 30237493, 2018). "Therefore, our findings uncover a molecular mechanism underlying CCL2 overexpression in the cancer cell and suggest that a neutralizing antibody against CCL2 will serve as an effective therapeutic approach for patients with LNMAT1-overexpressing bladder cancers." (PMID 30237493, 2018). "Overall, we found a molecular mechanism of CCL2 overexpression in the bladder cancer and showed that treatment targeting FAM171B would be an effective approach for bladder cancer patients with high TAM infiltration." (PMID 37915048, 2023). "In comparison to healthy donors, CCL2, IL-6, CXCL10, IL-1b, IFN-g, TGF-b, and IL-8 were enriched within the urine of bladder cancer patients." (PMID 37901214, 2023). "To further validate the effect of FAM171B/CCL2 modulation in vivo, we established a mouse subcutaneous transplantation tumor model using MB49 bladder cancer cells." (PMID 37915048, 2023). "The ELISA results revealed that overexpression of FAM171B increased CCL2 secretion and knockdown of FAM171B decreased CCL2 secretion in MB49 mouse bladder cancer cells." (PMID 37915048, 2023). "LncRNA-LNMAT1 epigenetically activated CCL2 expression, promoting recruitment of macrophages and metastases in the TME of bladder cancer." (PMID 31777603, 2019). "Local production of CCL2 (monocyte chemoattractant protein-1 (MCP-1)), in patients, correlated significantly with bladder cancer progression." (PMID 22013484, 2011). "Based on these results, we may speculate that loss-of-expression in SPOP might also stabilize PD-L1 protein in bladder cancer cells and induce immune escape via TAMs, beyond the STAT3/CCL2/IL-6 axis." (PMID 39479456, 2024). "Moreover, enhanced expression of CCL2 induces TAM activation and M2 polarization, which ultimately contribute to lymphangiogenesis and lymph node metastasis of bladder cancer cells by secreting vascular endothelial growth factor C (VEGF-C)." (PMID 36263199, 2022). "Moreover, LNMAT1-induced CCL2 regulated the TME through recruiting TAMs, ultimately resulting in lymphatic metastasis of bladder cancer." (PMID 31448238, 2019). "Moreover, LNMAT1-induced CCL2 modulated the tumor microenvironment through TAMs infiltration and VEGF-C upregulation in bladder cancer tissues, ultimately resulting in lymphangiogenesis and lymphatic metastasis." (PMID 30237493, 2018). "Finally, in bladder cancer, mast cells induce EMT in cancer cells via stimulation of the ERβ/CCL2/CCR2 axis." (PMID 28599100, 2017). "Furthermore, chemokines CCL2 and CXCL10, which contribute to immunosurveillance, were induced by shRNAs of PPARγ and RXRα in HT-1197 bladder cancer cells bearing endogenous RXRαS427F." (PMID 28740126, 2017).
bladder cancer (continued). "Furthermore, this lncRNA can induce the expression of CCL2 in bladder cancer cells, upregulate CCL2 to stimulate TAMs to secrete VEGF-C, participate in lymphogenesis, promote lymphatic metastasis and lymphangiogenesis, and accelerate the invasiveness of bladder cancer cells." (PMID 35145526, 2022).
fibrosis (67 papers, 2010 to 2026). the formation of excess fibrous connective tissue in an organ or tissue in a reparative or reactive process. "It demonstrated that intravenous administration of T. cruzi-derived neurotrophic factors in MyD88-knockout mice (deficient in TLR signaling) increased CX3CL1 and CCL2 levels, modulating inflammatory responses mediated by Trk signaling and reducing cardiac fibrosis." (PMID 40936920, 2025). "Mice with lung epithelial cell-specific deletion of Ccl12 are protected from bleomycin-induced fibrosis, showing decreased macrophage recruitment with Ccl2 and Ccl7 expression similar to control mice." (PMID 39768150, 2024). "Inflammatory damage triggers monocytes to secrete CCL2, recruiting white blood cells or macrophages to injury sites, ultimately leading to intestinal fibrosis." (PMID 39850880, 2024). "In relation to hepatic fibrosis and hepatocarcinogenesis, the expression of hepatic inflammatory cytokines (i.e., Tnf-α, Ccl2, and Il-6) was elevated in STAM mice, compared with DIO mice." (PMID 37852976, 2023). "CCL12, the CCL2 analog expressed in humans, was also elevated in the lungs of a fibrosis mouse model." (PMID 37524875, 2023). "Altogether, these data demonstrate that GILZ expression is lower in livers of human NASH and NAFLD patients presenting fibrosis compared to healthy controls, and that its expression inversely correlates with the expression of CCL2." (PMID 33927191, 2021). "Further, on day 28 of life we observed cardiac fibrosis by Sirius Red staining, which was accompanied by an increase in mRNA expression of galectin-3 and CCL2 (chemokine (C-C motif) ligand 2) in whole hearts of hyperoxic pups, which improved with IL-1Ra." (PMID 31354700, 2019). "In line, hepatic mRNA expression of the chemokines ccl2 (F0-1 compared to F4 fibrosis, p = 0.0088) and ccl5 (F0-1 compared to F4 fibrosis, p<0.0001), but not of ccl3, was strongly up-regulated in fibrosis." (PMID 20548789, 2010). "Targeting Ccl12 may be an antifibrotic strategy, as the Ccl12-Ccr2 axis drives fibrocyte influx and fibroproliferation in mouse fibrosis models, with Ccl12 neutralization being more effective than Ccl2 in protecting from FITC-induced fibrosis." (PMID 39768150, 2024). "The expression levels of CCL2 and CXCL2 were significantly lower in the lungs of BLM-induced NFATc3+/- fibrosis mice compared to those of NFATc3+/+ mice." (PMID 37523510, 2023). "Additionally, knockout of STAT6 in SSc mouse models significantly reduces the expression of CCL2 and CD206, indicating that CCL2 is involved in the immune response that drives skin and organ fibrosis." (PMID 39850880, 2024). "Clinical research has shown that CCR2+ (CCL2 receptor) macrophages and monocytes are extremely active in the lung and are located in the central area of fibrosis of IPF patients, indicating that CCL2/CCR2 plays an important role in the pathogenesis of fibrosis." (PMID 36556326, 2022). "The data indicate that Ccl2 overexpression promoted death in mice with accelerated aging and confirmed the role of Ccl2 as a fibrosis-inducing agent with a negative impact on biological outcomes associated with aging and/or longevity." (PMID 33104522, 2020). "In the present study, we observed increased levels of IL-8 and CCL2 in PBMCs from nAMD patients without fibrosis suggesting that IL-8 and CCL2 from PBMCs might reduce the risk." (PMID 28231837, 2017). "The CCR2-CCR5 antagonist, cenicriviroc, which blocks chemotactic signaling of CCL2 (MCP-1), CCL3 and 4 (MIP-1α and β), and CCL5 (RANTES), showed encouraging phase 2b study results of improving fibrosis without worsening NASH activity and a phase 3 study is currently under way." (PMID 30643981, 2019).
injury (67 papers, 2010 to 2026). Damage inflicted on the body as the direct or indirect result of an external force, with or without disruption of structural continuity. "CCL2 is a chemoattractant for HSCs and its expression is associated with fibrogenesis in both human cholestatic liver disease and in the bile-duct-ligated rat model of cholestatic liver injury." (PMID 20161726, 2010). "Consistent with this, our data showed that higher levels of CCL2 were associated with macrophage accumulation and recovery from APAP-induced liver injury." (PMID 39363292, 2024). "In this phase following nerve injury, the CCL2/CCR2 axis is essential in maintaining pain hypersensitivity." (PMID 39076996, 2024). "Inflammatory chemokine (C-C motif) ligand 2 (Ccl2; also known as monocyte chemoattractant protein-1 or MCP-1) is known to attract monocytes and T cells during liver injury." (PMID 39542242, 2024). "Immunohistochemical and other experimental results showed that the expression of TF, PAR1, CCL2, and IP-10 in the liver of drug-induced liver injury mice in the ConA group was higher than that in the untreated group and the YKL-40 low expression group." (PMID 37693903, 2023). "Although the association between CCL2 and these two antioxidant-related genes is unknown, C-C motif chemokine ligand 5, a member of the same chemokine family, has been shown to enhance glutathione peroxidase 1 antioxidant activity in mice with mild traumatic brain injury." (PMID 36992978, 2023). "It has been previously shown that C1-inhibitor protects from focal brain trauma in mice by reducing thrombo inflammation and diminishing upregulation of proinflammatory factors, such as CCL2, CCL3, IL-beta, and tumor Necrosis Factor alpha (TNF-α)." (PMID 33375205, 2020). "Inhibition of CCL2 signals attenuated microglial activation andpro-inflammatory cytokine production in animal models of brain injury." (PMID 23627909, 2013). "However, the mRNA levels of TF, PAR1, CCL2, and IP-10 in the drug-induced liver injury group mice induced by ConA were significantly higher than those in the other three groups." (PMID 37693903, 2023). "Furthermore, mice fed with a diet enriched in α-linolenic acid, the precursor of DHA, have higher brain DHA levels and produce less cortical proinflammatory cytokines and CCL2 24h post traumatic brain injury." (PMID 33801489, 2021). "Similarly, we also found that, compared to sham rats, IL-1β, CXCL1, CXCL11, CCL2, and transcription factor (Spil/Pu.1, Runx3, and IκBz) are obviously elevated at 7 days following nerve injury." (PMID 31708740, 2019). "Biomarkers that can be used in the diagnosis of kidney injury are kidney injury molecule-1 (KIM-1), neutrophil gelatinase-associated lipocalin (NGAL), matrix metalloproteinases (MMPs), and monocyte chemotactic protein 1 (MCP-1), also known as the chemokine CC motif ligand 2 (CCL2)." (PMID 34205319, 2021). "MKC (murine KC, CXCL1), MCP-1 (CCL2) and RANTES (CCL5) are chemokines that are involved in the pathogenesis of acute lung injury." (PMID 38474386, 2024). "All the results indicated that exogenous CCL2 is promising to restart neuroblasts migration even in both normal and CCI mice (day 28; the late phase of brain injury)." (PMID 36600294, 2023). "Mice lacking the CCR2 receptor for the chemokine MCP-1/CCL-2 fail to develop signs of neuropathic pain following nerve injury, a MCP-1/CCL2 antagonist blocks paclitaxel-induced neuropathic pain and over expression of CCR2 enhances nociceptive responses." (PMID 35295524, 2021). "It was recently described that CCL2 and its receptor CCR2 regulate macrophage trafficking by induction of leukocyte adhesion to the microvascular endothelium after brain injury." (PMID 31660990, 2019). "We confirmed that in a prophylactic setting, this reduction was mediated by the inhibition of CCL2 and CCL12 production and the partial inhibition of CXCL12 production, which are stimulated by lung injuries." (PMID 24507087, 2014).
injury (continued). "Increases in CCL2 inhibit HIV-Tat induced apoptosis in neurons and astrocytes and increased IL-10 facilitates neuronal recovery after traumatic brain injury by reducing inflammatory cytokine production." (PMID 22901451, 2012). "In addition, CCL2, CCL7, and CCL12 have been found in areas of the brain after traumatic brain injury." (PMID 35820932, 2022). "MCP1(CCL2, MCP-1; Monocyte Chemoattractant Protein-1 (MCP-1): In MCP-1 (−/−) db/db mice, kidney macrophage accumulation and the progression of diabetic renal injury were substantially reduced compared to MCP-1(+/+) db/db mice with equivalent diabetic conditions." (PMID 34576149, 2021). "Genes that encode inflammatory cytokines (such as TNF and IL1), chemokines (such as CCL2, CXCL1, CXCL2, and CXCL3) and cell proliferation-related proteins (such as CycD and CycE) were downregulated when Cyp2c29 was overexpressed in a mouse model of liver injury." (PMID 32587777, 2020). "Based on these data, we reasoned that TLR2-expressing satellite glial cells or macrophages in the DRG might respond to nerve injury and indirectly induce CCL2/MCP-1 expression in DRG neurons after peripheral nerve injury, thus enhancing macrophage infiltration." (PMID 21951975, 2011).
malaria (67 papers, 2005 to 2025). Malaria is a serious and sometimes fatal disease caused by a parasite that commonly infects a certain type of mosquito which feeds on humans. "We show during malaria age is associated with increased inflammatory chemokines CCL2, CCL3, CXCL8, CXCL9, along with CRP, and IDO, which associate with symptoms." (PMID 41027884, 2025). "The study aimed to offer insights into how MCP-1/CCL-2 contributes to malaria pathophysiology, with implications for diagnostic and therapeutic development." (PMID 39567619, 2024). "Monocyte chemoattractant protein-1 (MCP-1) or C-C Motif Chemokine Ligand 2 (CCL-2) is a key chemokine implicated in the inflammatory response to malaria." (PMID 39567619, 2024). "Studies from different continents, participant groups, Plasmodium species, and diagnostic methods for malaria show significant differences in MCP-1/CCL-2 levels." (PMID 39567619, 2024). "The high heterogeneity (I2 = 97.2%) indicates substantial variability in effect sizes across studies, which limits the potential of using MCP-1/CCL-2 as a reliable diagnostic biomarker for malaria." (PMID 39567619, 2024). "Increased CCL2 levels have been observed in malaria and canine babesiosis caused by B. rossi and B. canis." (PMID 36839438, 2023). "Additionally, we found that even in the uninfected control group, history of previous malaria episodes was associated with reduced perturbation of indirect bilirubin, total bilirubin, CCL2, CXCL10, IL-10 and IFN-γ." (PMID 34727121, 2021). "Factors such as parasite load, prior immunity, co-infections, and genetic predispositions all play a role in modulating the host’s immune response, and these must be carefully considered when interpreting the role of MCP-1/CCL-2 in malaria." (PMID 39567619, 2024). "Future research should focus on large-scale, well-designed studies to validate the role of MCP-1/CCL-2 in malaria and further explore its prognostic potential." (PMID 39567619, 2024). "This highlights the importance of considering the epidemiological and immunological background when interpreting the MCP-1/CCL-2 levels in patients with malaria." (PMID 39567619, 2024). "A systematic review and meta-analysis approach was employed to provide a robust assessment of MCP-1/CCL-2’s potential as a biomarker for malaria severity." (PMID 39567619, 2024). "Future studies should aim to integrate both clinical and immunological data to provide a more comprehensive understanding of how MCP-1/CCL-2 contributes to malaria pathogenesis and disease progression." (PMID 39567619, 2024). "The high levels of MCP-1/CCL-2 observed in participants with severe malaria underscore the dual role of this chemokine." (PMID 39567619, 2024). "This is a surprising result, as high levels of CXCL10 and CCL2 have been frequently reported as markers of severity and death during malaria and even CM." (PMID 36759905, 2023). "We previously reported HbSS patients infected with Pf had significantly decreased serum levels of IL-8 and the inflammatory ratio of CCL2:TNF compared to malaria infected HbAA patients." (PMID 36618355, 2022). "For cytokines IL-6, IL-1RA, IL-10 and IL-11 and chemokines CXCL1, CXCL8, CXCL10, CCL3 and CCL2, significantly higher concentrations were found in plasma samples of malaria patients compared to healthy controls." (PMID 34359826, 2021). "Using information from the canonical coefficients, we found that the IFN pathway exhibited a relevant role in the discrimination of symptomatic malaria and controls, with CCL2 followed by CXCL10 and CXCL9 as the top markers." (PMID 34727121, 2021). "Previous studies have reported increased levels of CCL3, as well as CCL2 and IL-8, have been reported in pregnant women with malaria." (PMID 33424841, 2020).